MIR6084 (microRNA 6084)
Synonyms: hsa-mir-6084
Gene: MicroRNA gene on chromosome 1 (20,633,679 to 20,633,788, forward strand). Ensembl gene ENSG00000284005.
Homologues: Orthologues: chimpanzee MIR6084 (100% identical).